INS (insulin)
Diseases named in the same sentence as INS in open-access papers (continued):
Sharing a sentence is not in itself a finding about the gene and the disease.
Insulin resistance (continued). "Taken together, the majority of studies (7 of 10 (70%), with 4 animal and 3 human studies) reported lower body weight, blood glucose, insulin level, and insulin resistance in association with helminth infections." (PMID 36827239, 2023). "Incretin hormones are responsible for enhancing the action of insulin, and, therefore, their deficiency leads to increased insulin resistance." (PMID 37445466, 2023). "It acts on insulin sensitivity, and its plasma lowering is associated with insulin resistance and glucose intolerance, hence increasing the risk of progressive liver injury." (PMID 37238961, 2023). "Third, elevated OBS values have the potential to enhance insulin sensitivity, facilitate efficient glucose utilization, and reduce the risk of insulin resistance, which is a crucial factor in the development of MetS." (PMID 37654473, 2023). "A study conducted by Hsing and colleagues unveiled a direct association between insulin resistance and an increased PCa risk, while insulin sensitivity was correlated with a diminished risk of PCa occurrence among Chinese men." (PMID 38068717, 2023). "A diet, that leads to an increase in blood sugar, is seem to be the major risk factor for insulin resistance, because it would potentially affect post-prandial insulin and lead to insulin resistance." (PMID 37996610, 2023). "This imbalance in hepatokines levels is associated with insulin resistance, glucose intolerance, ectopic lipid accumulation, inflammation, and impaired insulin secretion." (PMID 37274345, 2023). "A recent study has shown that a combination of three gene variants such as SLIT3, PLEKHA5, and PPP2R2C is a risk factor for insulin resistance and increases the probability of becoming insulin resistant by 50%." (PMID 37298715, 2023). "Insulin resistance (IR) and β cell dysfunction, such as deficiency in insulin secretion, are critical factors in the development of Type 2 diabetes." (PMID 37569125, 2023). "The VDR gene is implicated in the insulin metabolic pathway, and its polymorphism is linked to insulin resistance and secretion." (PMID 37836571, 2023). "It is mainly caused by insulin resistance or impaired insulin production and has reached epidemic proportions worldwide." (PMID 37349729, 2023). "The primary pathophysiological processes involved in the development of T2DM are a reduction in insulin secretion by β-cells and/or a decline in insulin sensitivity (insulin resistance), which causes the body to have high blood sugar levels (hyperglycemia)." (PMID 38004306, 2023). "Impaired lipolysis and resulting hypertrophy of adipocytes has been associated with systemic insulin resistance and elevated circulating insulin levels under metabolic syndrome condition." (PMID 38146533, 2023). "This insulin-independent mechanism of action allows for the administration of SGLT2 inhibitors to patients with various levels of beta-cell dysfunction or insulin resistance, minimizing the risk of hypoglycemia." (PMID 38002034, 2023). "Although physiologically IGF-1 improves glucose homeostasis, the chronic excess of GH in acromegaly that causes insulin resistance greatly exceeds the possible beneficial effects of IGF-1 on insulin sensitivity." (PMID 37628857, 2023). "Peripheral insulin resistance triggers CNS insulin signaling to worsen, which then causes changes in cerebral metabolism." (PMID 37445928, 2023). "Increased insulin, C-peptide, and HbA1c usually implied islet β-cell dysfunctions and insulin resistance, which was closely linked with dyslipidemia and amino acid transportation disorders." (PMID 37497350, 2023). "FA composition was correlated with the skeletal muscle response to insulin and obesity, and the level of unsaturation was linked to insulin resistance." (PMID 38132860, 2023).
Insulin resistance (continued). "Among the Asian population, even a small decline in insulin secretory function can result in a rapid decrease in the threshold level of insulin resistance and type 2 diabetes, which are strong risk factors for CVD." (PMID 37049580, 2023). "On the other hand, insulin resistance induced by dexamethasone is associated with several changes along the insulin signaling cascade." (PMID 37560158, 2023). "It is well established that mitochondria play a significant role in pancreatic insulin secretion, and consequently, mitochondrial dysfunction is linked to insulin resistance in T2D." (PMID 37508448, 2023). "In this paper, we aimed to address the role of PKN1 kinase in obesity-associated insulin resistance, in insulin signaling and in adipocyte biology." (PMID 37242297, 2023). "Several studies have linked insulin resistance and elevated insulin concentrations (outside of the normal range) to the IRS1 gene, which plays a vital role in insulin signaling." (PMID 38026570, 2023). "The insulin methylation index was associated with the newborn birth weight (r = 0.46; p = 0.033) and with insulin resistance (r = -0.533; p = 0.027) in the GDM group." (PMID 37264478, 2023). "RAAS blockers have been shown to boost insulin sensitivity, leading to a reduction in insulin resistance as well as associated inflammation." (PMID 37566054, 2023). "In men, low concentrations of testosterone are associated with obesity and adipose tissue insulin resistance, while in women, excess testosterone has an unfavorable effect on insulin sensitivity." (PMID 36979669, 2023). "Our approach provides opportunities to improve the identification of insulin-resistant individuals at risk of insulin resistance-related adverse health consequences." (PMID 37329449, 2023). "Both chronic and acute exposure to MC-LR caused a disruption of the insulin signaling pathway, which led to the upregulation of T2D-related genes, hyperinsulinemia, and insulin resistance." (PMID 37104227, 2023). "Pancreatic β-cell proliferation leads to higher levels of insulin, preventing hyperglycemia associated with insulin resistance and maintaining normoglycemia through a process known as β-cell compensation." (PMID 37935669, 2023). "In response to increased blood sugar, the β cells of the pancreas release a lot of insulin, causing a subfigures compensatory rise in insulin, which can lead to insulin resistance." (PMID 37569125, 2023). "The presence of DENV IgM was independently associated with insulin resistance (p = 0.26, 20% power), with a 1.58-fold higher chance of insulin-resistant individuals being positive for DENV IgM (OR: 1.58, 95% CI: 0.686–3.632)." (PMID 36680274, 2023). "Since hypothalamic insulin signal was reported to be implicated in the regulation of obesity and insulin resistance, we also investigated the neuronal insulin signalling and found the reduced phospho‐AKT level in neurons after Hnscr knockout in htNSCs." (PMID 36042571, 2023). "Overall, the liver-specific overexpression of Zfyve28 markedly impaired insulin sensitivity and led to worse metabolic and cardiovascular indicators associated with insulin resistance in mice." (PMID 37884540, 2023). "With increasing age, the fertility and organ function of pregnant women are reduced, and insulin sensitivity and pancreatic β-cell function are decreased, which in turn lead to insulin resistance (IR) and an increased risk of hyperglycemia." (PMID 36967760, 2023). "Increased systemic insulin levels and concomitant insulin resistance during the progression to type 2 diabetes is associated with chronic overactivation of the mTORC1 signaling pathway and cell stress in the context of a high protein synthesis rate." (PMID 37854186, 2023). "Β-cell apoptosis also plays a significant role in the pathogenesis of T2D along with obesity-associated insulin resistance and impaired insulin secretion." (PMID 38139235, 2023).
Insulin resistance (continued). "Diabetes is caused by impaired insulin production or insulin resistance and is manifested by persistent hyperglycemia." (PMID 37817864, 2023). "The mechanisms of vitamin D reducing the risk of T2D include, improved insulin sensitivity, and reduced insulin resistance." (PMID 36742396, 2023). "The hallmark of T2DM is elevated blood glucose levels and insulin resistance, accompanied by insufficient insulin secretion and dyslipidaemia." (PMID 37965545, 2023). "With de novo ceramide synthesis, ceramides derived from palmitic acid are the most potent at decreasing insulin action and causing insulin resistance." (PMID 37223039, 2023). "An in-depth understanding of the mechanisms of insulin resistance is necessary and important to improve insulin sensitivity and prevent associated metabolic and cardiovascular diseases." (PMID 37884540, 2023). "Smoking leads to insulin resistance and/or inadequate compensatory insulin secretion through various underlying effects, including oxidative stress, inflammation, and endothelial dysfunction." (PMID 37107279, 2023). "On the contrary, insulin suppression of hepatic glucose output is impaired in insulin resistance associated with type 2 diabetes and obesity leading to enhanced gluconeogenesis." (PMID 38129407, 2023). "In this study, we found that participants with vitamin D deficiency had higher levels of TG, AIP, TyG, insulin, and insulin resistance index and lower HDL-C." (PMID 37686729, 2023). "T1DM is the result of the destruction of pancreatic β cells which causes insulin deficiency, whereas T2DM is caused by reduced insulin secretion by pancreatic β cells and insulin resistance." (PMID 37372155, 2023). "In animal experiments, Gal3 administered to obese mice was shown to cause insulin resistance and glucose intolerance, whereas loss of Gal3 by genetic or pharmacologic means improved insulin sensitivity." (PMID 37175823, 2023). "Due to the lack of exact knowledge of the underlying mechanism of the relationship between insulin potential indices and insulin resistance with T2DM, more molecular and genetic studies are needed by taking into account different clinical factors." (PMID 37394447, 2023). "Higher levels of adiponectin have been linked to better insulin sensitivity, whereas lower levels have been linked to insulin resistance." (PMID 38004353, 2023). "This impairment of insulin signalling results in the development of hepatic insulin resistance, a pathological condition strongly associated with hepatic lipid accumulation and NAFLD." (PMID 37445956, 2023). "T2D is a metabolic disorder, caused by insulin resistance, the inability of cells to respond adequately to insulin, together with a progressive loss of insulin secretion from the beta cells in the pancreas." (PMID 37216359, 2023). "The expression of adiponectin, its induction by insulin, and its modulation of β-cell function form the basis of the association between adiponectin and insulin resistance/hyperinsulinemia." (PMID 37009872, 2023). "Insulin resistance promotes obesity; increasing adipocytes promotes cytokines to accelerate the catabolism of muscles; and loss of muscle reduces insulin-responsive tissues, which are complicated by insulin resistance." (PMID 37893082, 2023). "Previous targeted studies have associated insulin resistance with defects in proximal insulin signaling proteins, including AKT, IRS1/2, and the insulin receptor." (PMID 36808134, 2023). "T2DM, which is the most common type of diabetes mellitus, is associated with insulin resistance and impaired insulin production." (PMID 37755075, 2023). "Insulin resistance is a complex metabolic disorder associated with attenuated responsiveness of peripheral tissues (muscle, liver, adipose tissue) to insulin signaling; therefore, insulin release is increased to maintain glucose homeostasis." (PMID 37568381, 2023).
Insulin resistance (continued). "Oxidative stress causes outer blood–retinal barrier degeneration that contributes to AMD progression, and oxidative stress is a risk factor for the development of insulin resistance through insulin signal disruption." (PMID 38074151, 2023). "Insulin resistance is linked to high amounts of endogenous insulin, which leads to weight gain, eventually exacerbating insulin resistance." (PMID 37346347, 2023). "Obesity is positively correlated with insulin resistance, which affects the proliferation and differentiation of thyroid cells through insulin secretion and is significantly associated with the formation of TNs." (PMID 37728058, 2023). "An important pathological manifestation of PCOS is insulin resistance (IR), which is associated with defective insulin activity and secretion." (PMID 38102584, 2023). "The primary cause of T2DM is a gradual decline in insulin secretion by pancreatic β-cells, typically occurring against a backdrop of pre-existing insulin resistance in skeletal muscle, liver, and adipose tissue." (PMID 38004353, 2023). "Hyperglycemia can be caused by inefficiency in insulin action (also known as insulin resistance), secretion (also known as insulin deficiency), or both, as well as perturbations in the metabolism of carbohydrates, fats, or proteins." (PMID 36896239, 2023). "Compared to type 1 diabetes (T1DM), which is featured by insufficient insulin production by the pancreas, pancreatic β‐cell dysfunction, and insulin resistance are hallmark features of T2DM patients." (PMID 36721851, 2023). "For example, SHP-1 has been implicated in the modulation of insulin signaling and insulin resistance." (PMID 37595871, 2023). "It is well known that greater skeletal muscle mass is associated with increased insulin sensitivity while sarcopenia is known to be related to insulin resistance." (PMID 37768516, 2023). "Given the central metabolic role of skeletal muscle in insulin-mediated glucose disposal, disruption of insulin signaling in this tissue is considered one of the possible major causes of systemic insulin resistance in PCOS." (PMID 37371678, 2023). "Chemotherapy drugs can also cause a decrease in insulin production or insulin resistance, which can lead to higher blood sugar levels." (PMID 37165049, 2023). "ROS are able to activate cellular signaling pathways such as specific protein kinase C (PKC) isoforms, including PKC-βII or nuclear factor-κB (NF-κB), and afterward disturb insulin signaling pathways that cause insulin resistance." (PMID 37298715, 2023). "A decrease in the activity of the insulin signaling system of the brain, due to both central insulin resistance and insulin deficiency, leads to neurodegeneration and impaired regulation of appetite, metabolism, endocrine functions." (PMID 36834685, 2023). "Insulin resistance is also caused by a reduced tendency for insulin to bind to its receptor in an acidic environment, which is directly related to the risk of CVD and all‐cause mortality." (PMID 36911829, 2023). "Inflammation from the adipose tissue causes insulin resistance, and insulin triggers cancer through antiapoptotic effects." (PMID 36860687, 2023). "The associations between SJL and metabolic risk factors such as fasting insulin, glucose, triglycerides, insulin resistance and lipid profiles are well established." (PMID 37528259, 2023). "Pdk4 expression has been shown to be increased in skeletal muscle and heart of obese, insulin resistant, and diabetic animal models, and to be associated with insulin resistance and cardiac dysfunction." (PMID 37626210, 2023). "Among numerous genetic loci, TCF7L2 (rs7903146), KCNQ1 (rs2237892), and KCNJ11 (rs5219) are associated with β-cell function, insulin resistance, and insulin action in GDM." (PMID 37107681, 2023). "Considering the importance of muscle mass in whole-body responses to insulin, individuals who are prone to muscle mass loss are more likely to develop insulin resistance." (PMID 37876013, 2023).
Insulin resistance (continued). "The activation of JNK can further activate the transcriptional regulator AP-1 and induce the expression of inflammatory genes, such as IL-6 and TNF, inhibiting insulin signaling and causing insulin resistance." (PMID 36875140, 2023). "The involvement of VEGF-A in glucose homeostasis is well-known, as low levels of the biomarker are linked to insulin resistance, while its overexpression is associated with impaired insulin production and increased glucose levels." (PMID 37111103, 2023). "Abdominal obesity related to increasing waist circumferences is linked to an elevated insulin resistance, which requires increased insulin secretion to maintain glucose homeostasis." (PMID 37049581, 2023). "Type II Diabetes (T2D) is characterized by a progressive loss of insulin secretion by β cells in the pancreas due to insulin resistance (American Diabetes)." (PMID 37104227, 2023). "Insulin resistance leads to hypertension through the loss of the vasodilatory effect of insulin and amplification of vasoconstriction due to FFA through reactive oxygen species." (PMID 36677012, 2023). "Insulin resistance combined with the use of exogenous insulin causes the activation of the mitogen-activated protein kinase (MAPK) pathway." (PMID 37065759, 2023). "Under conditions of insulin resistance, as in type 2 diabetes (T2D), or insulin deficiency, as in type 1 diabetes (T1D), insulin stimulated skeletal muscle uptake is reduced." (PMID 37626210, 2023). "Insulin resistance and decreased insulin secretion cause hyperglycemia and many other issues related to obesity that worsen the state of the disorder such as elevated free fatty acids and ectopic fat accumulation." (PMID 37049602, 2023). "Insulin resistance and β-cell dysfunction synergistically enhance the degree of hyperglycemia and culminate in a relative deficiency of insulin." (PMID 36766803, 2023). "It is known that an increased body mass is associated with increased levels of insulin and insulin resistance." (PMID 37298551, 2023). "It is known that genetic factors, which affect metabolic pathways involved in adipogenesis, fat distribution, insulin signaling, and insulin resistance, can modulate the predisposition of developing obesity-related complications and lead to MUO." (PMID 36982283, 2023). "Analyses with intermediate traits showed a probable causal relationship with fasting insulin, a measure of insulin resistance known to be linked to fitness." (PMID 37400433, 2023). "It is caused by insulin resistance, which is impaired insulin action in target tissues, and insufficient secretion of insulin from pancreatic β-cells." (PMID 38004168, 2023). "Insulin secretion defects and insulin resistance, triggered by chronic and excess nutritional intake, cause glucose intolerance and hyperglycemia." (PMID 37111216, 2023). "PTP1B belongs to the intracellular PTPs expressed in various cells and tissues, and its encoding gene, PTPN1, is located in a region associated with insulin resistance and obesity; hence, it is involved in the regulation of the insulin metabolic pathways." (PMID 37686185, 2023). "Type 2 diabetes is a chronic condition which causes hyperglycemia, insulin resistance and impairment of the way the body responds to the stimuli of insulin." (PMID 37103396, 2023). "Hyperglycemia, which can be caused by either an insulin deficit and/or insulin resistance, is the main symptom of Type 2 diabetes, a significant endocrine metabolic illness." (PMID 36936164, 2023). "In this sense, higher PTP1B expression in tissues impairs the ability of insulin to bind to its receptor, inducing insulin resistance and causing obesity and T2DM." (PMID 37383489, 2023). "The abnormal expression of IGFs, increased insulin levels and insulin resistance trigger the mechanisms associated with the development of various malignant tumors." (PMID 37298551, 2023).